ZNF818P (zinc finger protein 818, pseudogene)
Description:
May be involved in transcriptional regulation.
Synonyms: FLJ46385; formerly ZNF818
Gene: Transcribed unprocessed pseudogene on chromosome 19 (53,204,016 to 53,214,522, forward strand). Ensembl gene ENSG00000269001.
Subcellular location: Nucleus